FTO (FTO alpha-ketoglutarate dependent dioxygenase)
Diseases named in the same sentence as FTO in open-access papers (continued):
Sharing a sentence is not in itself a finding about the gene and the disease.
Obesity (continued). "The results of this study showed that a haplotype in the first intron of the FTO gene had a strong association with obesity indices among Iranian adolescent males." (PMID 29677190, 2018). "Previous GWAS data had indicated that variants within introns of the FTO gene were associated with obesity." (PMID 29741584, 2018). "Although FTO is an established genetic susceptibility locus for obesity, the extent to which dietary factors modify this association has been unclear." (PMID 29484031, 2018). "The results of this study showed that a haplotype in the first intron of the FTO gene had a strong association with obesity indices in Iranian adolescent boys after adjustments for calorie intake and physical activity." (PMID 30126381, 2018). "Gene variants in MC4R and FTO are associated with severe obesity and metabolic impairment in Caucasians." (PMID 28133617, 2017). "With regard to the close association of IRX3 with the FTO obesity-linked loci, revealing IRX3's genetic profile can be of great importance to explain how genetic factors manipulate body weight alteration." (PMID 28988979, 2017). "Up to now, numerous case-control studies have reported the associations between fat mass and obesity associated (FTO) gene rs9939609 A/T polymorphism and polycystic ovary syndrome (PCOS), however, without a consistent result." (PMID 28826396, 2017). "Among the 225 obesity-associated SNPs collected in this study, 15 are positioned in the FTO locus, and all of them are within the first intron of FTO and increase obesity risk." (PMID 29126384, 2017). "In recent years, a total of more than 100 candidate genes have been set out to explore the associations between single nucleotide polymorphism (SNP) and PCOS, such as fat mass and obesity associated (FTO) gene." (PMID 28826396, 2017). "This review examines the biology of the Fat mass- and obesity-associated gene (FTO), and the implications of genetic association of FTO SNPs with obesity and genetic aging." (PMID 28859657, 2017). "FTO was first associated with obesity in a series of population studies that linked variations in the first intron of FTO to elevated BMI." (PMID 28533023, 2017). "In a large all-adult and area-based population survey the effects of obesity-promoting minor-alleles of FTO and MCR4, and interactions with life style factors are age- and gender-related." (PMID 28384342, 2017). "All participants were genotyped for FTO SNP rs9939609; thirty-six (17.9%) were homozygous for the obesity risk allele (AA), 90 (44.8%) were heterozygous (AT), and 75 (37.3%) were wild type (TT)." (PMID 28607773, 2017). "The FTO (fat mass- and obesity-associated) gene is a good candidate gene for T2DM and MetS, since its possible link to obesity with genome wide association study based evidence." (PMID 28915859, 2017). "We demystified association and interaction between FTO rs9939609, obesity, PA, TSS, and energy intake in Nigeria." (PMID 28607773, 2017). "Obesity is a heritable disorder, and some of the many obesity susceptible genes are fat mass and obesity (FTO), leptin, and Melanocortin-4 receptor (MC4R)." (PMID 28924523, 2017). "Subsequently, the following studies confirmed the positive associations between single nucleotide polymorphisms (SNPs) in/near FTO gene and obesity risk in diverse populations." (PMID 28881622, 2017). "There are other SNPs which are associated with obesity phenotypes, whereas our study included only six SNPs of the FTO gene." (PMID 28954439, 2017). "Our results are in tandem with previous studies as carriers of risk alleles showed higher obesity-related traits, thus confirming the relationship between FTO rs9939609 and obesity." (PMID 28607773, 2017). "Our study indicated that FTO genotype showed the strongest interaction (Pinteraction < 0.001) among all obesity predisposing variants." (PMID 28387720, 2017).
Obesity (continued). "Despite the high prevalence of obesity in Mexico, the FTO risk allele is considerably less frequent, both in admixed and Native populations as compared to Europeans (0.21, 0.06 and 0.46, respectively)." (PMID 28464932, 2017). "In another study the level of β2GPI in the adipose tissue in individuals with the pro-obesity FTO polymorphism was upregulated." (PMID 29190946, 2017). "FTO polymorphism with obesity-related traits has also shown association with increased body weight, leptin levels, and waist circumference." (PMID 28924523, 2017). "Other GWAS have linked FGF21 and the fat mass and obesity-associated gene, FTO, to macronutrient-specific preferences." (PMID 29053636, 2017). "FTO has been clearly identified as an obesity associated gene via Genome Wide Association Study (GWAS)." (PMID 28859657, 2017). "Fat mass and obesity associated (FTO) is the most investigated gene in obesity and has complex molecular mechanisms that are yet to be elucidated." (PMID 28103813, 2017). "Different polymorphisms in the FTO-gene intron 1 have been associated with obesity or with BMI in genomic scans as well as in models of simple association in different populations." (PMID 28690685, 2017). "These mainly include genes that are involved in energy balance, appetite regulation, and adipogenesis, i.e., fat mass and obesity-associated protein gene (FTO), and genes in the leptin–proopiomelanocortin pathway and uncoupling protein families." (PMID 28615046, 2017). "Single nucleotide polymorphisms in the m6A eraser alpha-ketoglutarate dependent dioxygenase (FTO), a gene that traditionally has been associated with obesity, have been associated with melanoma and estrogen receptor-negative breast cancer." (PMID 28798901, 2017). "As the genetic association to obesity at the FTO locus was reported to be age dependent, we also examined the role of age in our age-diverse group (range from 20 to 77)." (PMID 28662178, 2017). "We expectedly confirm an overall obesity-promoting effect of the FTO and MC4R minor-alleles in our study population." (PMID 28384342, 2017). "Individuals with the FTO risk allele (A) and low PA level had significantly high obesity risk factors (BMI, WC, NC, WHR, WHtR, body weight, 2D : 4D, energy intake, and TSS)." (PMID 28607773, 2017). "We find robust evidence of interaction with physical activity for the strongest known obesity risk-locus in the FTO gene, of which the body mass index-increasing effect is attenuated by ~30% in physically active individuals compared to inactive individuals." (PMID 28448500, 2017). "The strongest genetic association with risk to polygenic obesity is in SNPs in intron 1 and 2 of the FTO (fat mass and obesity associated) gene." (PMID 28507607, 2017). "Variations within fat mass and obesity associated (FTO) gene had crosstalk with obesity risk in European and some Asian populations." (PMID 28915859, 2017). "The rs9939609 obesity-risk allele of the FTO gene was reported to be associated with sucrose and protein preferences, high-fat and low fiber intakes, and carbohydrate and protein intakes." (PMID 29053636, 2017). "Although the strong association between FTO variations and obesity has been continuously reported, the genetic defects of the IRX3 gene per se on obesity have not been clarified until now." (PMID 28988979, 2017). "The objective of the present study is to determine (by means of case-control association analysis) in what manner the polymorphic risk variants in FTO/IRXB region affect obesity and/or overweight in the Polish population." (PMID 28662178, 2017). "The strongest obesity-associated loci were consistently identified as located in the first and second introns of FTO." (PMID 28988979, 2017). "The FTO rs9939609 gene variant has been consistently associated with BMI and obesity, however clear population differences have been identified." (PMID 28464932, 2017).
Obesity (continued). "Although those 15 obesity-associated SNPs are located within the first intron of FTO, it should be noted that some of the variants can form long-range functional connections with the homeobox gene IRX3, which is a half-megabase downstream of the variants." (PMID 29126384, 2017). "Among such polymorphisms, the FTO rs17817449 gene SNP showed to be associated with obesity in several populations." (PMID 29937877, 2017). "In the present study, we propose a model of interactions between genetic vulnerability—represented by Fat Mass and Obesity-Associated (FTO) gene—and stable psychopathological traits, such as bodily disorders and emotion dysregulation for EDs patients." (PMID 28282466, 2017). "Our aim was to assess the influence of age, gender and lifestyle factors on the effect of the obesity-promoting alleles of FTO and MCR4." (PMID 28384342, 2017). "Here, we provide a novel mechanism by which AMPK regulates skeletal muscle lipid accumulation through fat mass and obesity-associated protein (FTO)-dependent demethylation of N6-methyladenosine (m6A)." (PMID 28176824, 2017). "Previous studies have examined the association between the fat mass and obesity-associated (FTO) gene variant and risk of cancer in diverse populations." (PMID 28881622, 2017). "In an Asian Indian population, carbohydrate and fiber intake modulated the association of FTO SNPs rs8050136 and rs11076023 with obesity traits." (PMID 28954439, 2017). "For example, in adults, the allele (A) of the FTO variant, rs9939609, increased the risk of obesity in a meta-analysis of pooled populations, but physical activity attenuated this effect." (PMID 29126384, 2017). "Depletion of FTO (fat mass and obesity-associated protein) results in an increased mRNA m6A level, while overexpression of FTO leads to a decreased m6A level." (PMID 28176824, 2017). "Among FTO SNPs involved in this mechanism and associated with obesity, rs9939609 (located 82.431kb downstream of ATG start codon) is the most frequently described." (PMID 28282466, 2017). "The strongest effect on obesity occurred again with FTO variants: rs1558902 and rs1421085 in females using a dominant model (p = 0.000463 and p = 0.0004744 respectively)." (PMID 28662178, 2017). "FTO gene variant was genotyped by restriction fragment length polymorphism and gene sequencing analysis in 103 people with obesity and 98 controls." (PMID 28607773, 2017). "Significant associations were found between FTO rs9939609 with obesity and environmental/lifestyle variables before and after adjusting for age." (PMID 28607773, 2017). "Numerous studies confirmed the association between FTO common variants and obesity phenotype in many different populations." (PMID 28662178, 2017). "In a group of males, two different FTO loci, rs12149832 and rs9930506, showed the strongest association with obesity under the recessive model (p = 0.003137 and 0.003741, respectively)." (PMID 28662178, 2017). "FTO gene variants have been associated with obesity phenotypes in sedentary and obese populations, but rarely with skeletal muscle and elite athlete phenotypes." (PMID 28103813, 2017). "Chromosomal region 1q25 and FTO were previously identified as susceptibility loci for BMI and obesity." (PMID 28445147, 2017). "Although a number of studies have suggested that genetic polymorphisms in the fat mass and obesity-associated (FTO) gene are associated with T2DM risk, the results have been inconsistent." (PMID 28208657, 2017). "Multiple studies have also focused on deciphering potential mechanisms, by which variants within a region of high LD in introns 1 and 2 of FTO confer the obesity risk." (PMID 28662178, 2017). "Recent genome-wide association studies (GWAS) have identified several common single nucleotide polymorphisms (SNP) in the human FTO gene associated with obesity, body mass index BMI;, cardiovascular disease and hypertension." (PMID 28103813, 2017).
Obesity (continued). "Obviously, the role of genetic variation at the FTO locus in predisposing to obesity in Asian, Saudi, populations warrants further investigation especially in relation to the epidemiological transition and access to a calorie-rich diet." (PMID 29937877, 2017). "There is now convincing epidemiological evidence of interactions between common variants in the FTO (Fat mass and obesity-associated protein) gene and lifestyle with respect to obesity." (PMID 28210884, 2017). "Cross-sectional analyses focusing on lifestyle interactions with genetic risk scores comprised of other obesity-associated loci have also been widely replicated, although the extent to which those interactions are driven by FTO is rarely described." (PMID 28124081, 2017). "Here we designed a study for the associations between FTO (rs9939609) and obesity, including gene-environment interactions, based on data from HUNT3 (2006–2008)." (PMID 28384342, 2017). "The strongest genomewide association signal lies in introns 1 and 2 of the gene Fat Mass and Obesity Associated variant (FTO), which has been found to repress mitochondrial thermogenesis in adipocyte precursor cells." (PMID 29190946, 2017). "Of these factors, the fat mass and obesity–associated (FTO) gene is now recognized as the strongest common genetic predictor of obesity." (PMID 29273742, 2017). "FTO has been reported to be associated with obesity, and recent studies have shown the association of some FTO SNPs with GDM, like rs8050136 or rs9939609; however, to our knowledge, no studies on rs1421085 have been previously reported." (PMID 28507607, 2017). "Nevertheless, the search for PA interactions with obesity-associated loci only provided significant results with the FTO gene, showing a decrease of 30% of FTO effect in active as compared to sedentary subjects." (PMID 28829397, 2017). "FTO SNPs were associated with obesity in recessive model and dominant model for females and males, respectively." (PMID 28662178, 2017). "In 2007, a genome-wide association study reported that FTO is associated with body mass index (BMI) and obesity." (PMID 28826396, 2017). "Our findings suggest that Med Diet adherence can be useful for prevention or treatment of obesity phenotypes in subjects with FTO risk alleles." (PMID 28954439, 2017). "PMCA was also successfully applied to identify the causal variant and a potential disease mechanism at the obesity-associated FTO locus, a region showing the strongest genetic association in GWAS for obesity and body mass index traits." (PMID 28758174, 2017). "Of note, none of the CpGs associated with BMI was near genes previously identified in GWASs of obesity-related traits, such as FTO (fat mass and obesity associated) or MC4R (melanocortin 4 receptor)." (PMID 28095459, 2017). "We aimed to elucidate the association between fat mass and obesity associated gene (FTO) polymorphism and the risk of polycystic ovary syndrome (PCOS) by meta-analysis." (PMID 28451524, 2017). "In the present study, polymorphisms in the FTO gene (rs3751812, rs8050136, andrs9939609) were found to be significantly associated with BMI, obesity, MS, LDL, and cholesterol levels in the general control Kazakh cohort." (PMID 28738793, 2017). "This study was aimed at investigating the interaction of the Mediterranean dietary pattern (Med Diet) with FTO polymorphisms in relation to obesity phenotypes." (PMID 28954439, 2017). "A meta-analysis has shown that physical activity attenuated the influence of FTO variants on obesity in adults." (PMID 28387720, 2017). "Our greatest finding from this study was sex-dependent manner of FTO associations with obesity/overweight phenotype." (PMID 28662178, 2017). "Single-nucleotide-polymorphisms (SNPs) of the FTO (fat mass and obesity associated) gene have been associated with obesity." (PMID 28507607, 2017). "Global germ line loss of fat mass- and obesity-associated (FTO) gene results in both the reduction of fat mass and lean mass in mice." (PMID 28333151, 2017).
Obesity (continued). "In 2007, the fat mass and obesity associated (FTO) gene was reported as the first obesity related gene by the genome-wide association studies (GWAS) in Caucasian population." (PMID 28881622, 2017). "Such regulatory signaling within beige fat has been implicated as being disrupted with the FTO obesity variant in humans, promoting a pro-obesity phenotype." (PMID 29190946, 2017). "Among these, great interest has been recently devoted to the Fat Mass and Obesity-Associated (FTO) gene, previously implicated in obesity within several association studies, as a possible candidate for playing a role in the pathogenesis of EDs." (PMID 28282466, 2017). "An alternate explanation for the discrepancy in FTO SNP polymorphisms and regulation of energy expenditure is via the effect of the obesity-associated FTO region on expression regulation of homeobox gene IRX3 (Iroquois homeobox protein 3) and IRX5." (PMID 28859657, 2017). "Polymorphisms of the FTO gene are shown to be the strongest genetic determinant of obesity compared with the > 40 other genes which affect body weight." (PMID 28384342, 2017). "The fat mass and obesity associated (FTO) gene is a likely example of a regulatory “master switch” gene that influences epigenetic control over a number of key regulatory pathways in obesity regulation." (PMID 28859657, 2017). "When the authors compared 76 variants (53 independent) from the AN results with 89 established BMI/obesity SNPs, FTO variant and other 4 SNPs (inside other genes) had P<0.05 (binomial P = 0.1906)." (PMID 28282466, 2017). "The second candidate gene studied was the Fat Mass and Obesity associated protein (FTO), which confers risk for obesity and BMI." (PMID 28953253, 2017). "The fat mass and obesity-associated gene (FTO) as an obesity candidate gene has been related to PCOS susceptibility." (PMID 28451524, 2017). "Recently, two studies made a breakthrough in identifying IRX3 as the target of the risk loci in the FTO gene for human obesity." (PMID 28988979, 2017). "In the present study, we found that among those who were physically inactive, the minor allele carriers of the FTO SNP rs8050136 had higher risk of obesity." (PMID 27274759, 2016). "Association analysis after BMI stratification showed that all five FTO SNPs (rs1121980, rs17817449, rs3751812, rs9930506, and rs17817449), were significantly associated with obesity class II/III under an additive model (P<0.05)." (PMID 26726774, 2016). "For seven metabolites, we observed a significant genotype effect on obesity and T2D in FTO risk allele carriers compared with control subjects." (PMID 27249024, 2016). "To date, FTO has shown the strongest association with BMI, where the FTO SNPs increased the risk of obesity by 1.20–1.32 fold in Europeans and by 1.25 fold in Asians." (PMID 27274759, 2016). "FTO is the fat mass and obesity-associated gene but, in spite of its name, the exact physiological function of FTO is not well known." (PMID 26908368, 2016). "A trend can be observed wherein the carriers of FTO minor (risk) alleles at the three examined loci who are engaged in regular PA are at reduced obesity risk compared to those rare variants carriers who are associated with decreased levels of PA." (PMID 26908368, 2016). "It has been reported that the presence of two alleles at the rs9939609 site of the FTO gene increased BMI by about 1 kg/m2, body mass by 2.3Kg and 1.3-fold higher risk of overweight and obesity in both adults and children." (PMID 26878843, 2016). "Common variants in the fat mass and obesity associated (FTO) gene are linked to body mass index (BMI)." (PMID 27596730, 2016). "The fat mass- and obesity-associated (FTO) gene has provided strong evidence of the genetic susceptibility to obesity." (PMID 26851191, 2016). "Known obesity-associated variants in FTO showed strong evidence of deviation from additivity (pDOMDEV = 3 × 10−5) through a recessive effect of the allele associated with higher BMI." (PMID 26961502, 2016).